TTC17 (tetratricopeptide repeat domain 17)
Description:
Plays a role in primary ciliogenesis by modulating actin polymerization.
Synonyms: FLJ10890
Tractability: Antibody: UniProt places it where antibodies can reach, with high confidence; its Gene Ontology location is reachable by antibodies, with high confidence; the Human Protein Atlas places it where antibodies can reach. PROTAC: ubiquitination databases record sites on it; its protein half-life has been measured.
Gene: Protein-coding gene on chromosome 11 (43,358,920 to 43,494,933, forward strand). Ensembl gene ENSG00000052841.
Subcellular location: Cytoplasm; Cell membrane; Cytoplasm, cytoskeleton
Subcellular location (Human Protein Atlas): Plasma membrane; Cytosol
Gene Ontology:
Molecular function: protein binding
Biological process: actin filament polymerization; cilium organization
Cellular component: actin cytoskeleton; cytoplasm; plasma membrane; cytoskeleton
Genetic constraint (gnomAD): Loss-of-function variants: 50 observed, 131.44 expected, observed/expected ratio (o/e) 0.38, 90% interval 0.3 to 0.48. The upper end of that interval is the gene's LOEUF score, 0.48, which puts it in group 2 of 6, group 1 being the genes least tolerant of losing a copy. Missense variants: 1,195 observed, 1,350.2 expected, observed/expected ratio (o/e) 0.89, 90% interval 0.84 to 0.93. Synonymous variants: 479 observed, 489.56 expected, observed/expected ratio (o/e) 0.98, 90% interval 0.91 to 1.05.
Homologues: Orthologues: chimpanzee TTC17 (99% identical), macaque TTC17 (99% identical), dog TTC17 (98% identical), pig TTC17 (98% identical), guinea pig TTC17 (97% identical), mouse Ttc17 (96% identical), rat Ttc17 (95% identical), rabbit TTC17 (94% identical), tropical clawed frog ttc17 (72% identical), zebrafish ttc17 (62% identical), Caenorhabditis elegans ttc-17 (26% identical), Drosophila melanogaster CG11436 (12% identical).
Diseases named in the same sentence as TTC17 in open-access papers:
TTC17 is named in the same sentence as 18 diseases in open-access papers, as found by Europe PMC text mining. Sharing a sentence is not in itself a finding about the gene and the disease. The quoted sentences say what the papers report.
breast carcinoma (4 papers, 2019 to 2025). "Drugs losing sensitivity to BC cells with low TTC17 expression are suggested to be avoided in future use in TTC17-deficient breast cancers." (PMID 36895029, 2023). "The effects of tetratricopeptide repeat domain 17 (TTC17) downregulation on the invasiveness and metastasis of breast cancer were shown to be linked to activation of the Rap1/CDC42 pathway." (PMID 41303422, 2025). "We next established an orthotopic mouse mammary carcinoma model in female BALB/c mice using TTC17-knockout 4T1 cells to determine the influence of TTC17 on metastatic lung colonization." (PMID 36895029, 2023). "Based on the preliminary experimental results that TTC17 had a more obvious and stable effect on the malignant phenotype of breast cancer than other candidate molecules and our literature review assessing the current status of few studies on TTC17, we finally chose TTC17 for further study." (PMID 36895029, 2023). "Five genes (DPH2 G3BP1, G3BP2, NSUN2, and TTC17) were similarly regulated by SK1 KD in prostate and breast cancer cells." (PMID 30971929, 2019). "It suggests that upregulated DPP9, LRRC20 and TTBK2 together with downregulated TTC17, ZNF75D and CYTH2 may play pivotal role in the orchestrated adaptive homing of metastatic breast cancer cells in bone niche." (PMID 35685372, 2022).
bladder carcinoma (1 paper, 2023). "With regard to prognosis, reduced TTC17 expression was also correlated with shorter RFS in ovarian cancer and testicular germ cell tumors, together with dismal OS in bladder carcinoma, pancreatic ductal adenocarcinoma, rectum adenocarcinoma, and stomach adenocarcinoma." (PMID 36895029, 2023).
breast neoplasm (1 paper, 2023). A benign or malignant neoplasm of the breast parenchyma. "Moreover, compared to their respective counterparts, breast neoplasms with larger primary lesions, lymph node involvement, distant metastasis, or advanced TNM stage had lower TTC17 expression." (PMID 36895029, 2023). "To address the contribution of TTC17/RAP1/CDC42 activation to metastasis in patients with BC, we detected the protein expression of TTC17 and CDC42 in a large cohort of nonmetastatic and metastatic primary breast tumors together with their metastatic lymph node tissues." (PMID 36895029, 2023).
cerebral malaria (1 paper, 2021). A sequestration of Plasmodium falciparum in the brain, which can cause coma and/or seizures. "Similarly, the K-TSPs model for cerebral malaria identified nine gene pairs including: TTC17-C18orf8, PUM2-ASB7, RABEP1-MYH11, SETX-SPATS2L, XRCC5-TRIP12, ELF2-CHRNA10, LARP4-ANK2, MREG-KPNA6, and ZNF197-CD53." (PMID 34746025, 2021).
cervical squamous cell carcinoma (1 paper, 2023). A squamous cell carcinoma arising from the cervical epithelium. "Nevertheless, low TTC17 expression exhibited opposite effects on RFS in kidney renal papillary cell carcinoma and OS in cervical squamous cell carcinoma, kidney renal clear cell carcinoma, kidney renal papillary cell carcinoma, and pheochromocytoma and paraganglioma." (PMID 36895029, 2023).
ciliopathies (1 paper, 2014). "Based on our results, we propose to add C2orf62 and TTC17 to the list of candidate genes for ciliopathies of unknown etiology." (PMID 24475127, 2014).
esophageal squamous cell carcinoma (1 paper, 2022). Esophageal squamous cell carcinoma (ESCC) is a type of esophageal carcinoma (EC) that can affect any part of the esophagus, but is usually located in the upper or middle third. "Circ-TTC17 was found to enhance the progression of esophageal squamous cell carcinoma by promoting proliferation and migration." (PMID 35685372, 2022).
metastatic tumors (1 paper, 2023). "Research on BC specimens demonstrated reduced TTC17 and increased CDC42 in metastatic tumors and lymph nodes, and low TTC17 expression was linked to more aggressive clinicopathologic characteristics." (PMID 36895029, 2023).
ovarian carcinoma (1 paper, 2023). A malignant neoplasm originating from the surface ovarian epithelium. "Additionally, high TTC17 expression foreshadows improved RFS of BC, ovarian cancer, and testicular germ cell tumors, suggesting the special role of TTC17 dysfunction in the initiation and progression of these neoplasms involving reproduction." (PMID 36895029, 2023).
tumor (4 papers, 2020 to 2024). "In ESCC, circ-SLC7A5, circ-LRP6 and circ-TTC17 have been reported to play tumor-promoting roles, but circFoxo3 and circSMAD7 act tumor-inhibiting roles." (PMID 38514579, 2024). "RNAi-mediated silencing of TTC17 significantly impairs cilia formation, which is relevant to cancer biology given that cytoskeletal remodeling controls tumor cell motility and invasion." (PMID 36895029, 2023). "In BC specifically, TTC17 mRNA and protein expression levels were decreased in the tumor tissues relative to juxta-tumoral tissues." (PMID 36895029, 2023). "Pharmacological blockade of CDC42 abrogated the compelling difference in migration and invasion ability between MDA-MB-231 cells with TTC17-knockdown shRNA or scramble control, thereby confirming that the TTC17-mediated RAP1/CDC42 pathway was responsible for tumor progression." (PMID 36895029, 2023). "Pancancer analysis suggested that TTC17 was mostly downregulated in neoplasms compared to their normal counterparts." (PMID 36895029, 2023). "Moreover, circ-TTC17 in plasma was reported without any aberrant relationships to tumor size, differentiation, gender, age, or common clinical biomarkers (e.g., SCCA, CEA, and AFP) in ESCC cases." (PMID 33392180, 2020).
cancer (2 papers, 2019 to 2023). A tumor composed of atypical neoplastic, often pleomorphic cells that invade other tissues. "To date, research on TTC17 regarding its value in cancer biology and treatment is limited, and to our knowledge, the close association of TTC17 and BC is revealed here for the first time." (PMID 36895029, 2023). "The present study is the first report of TTC17 on its cancer-related function and potential treatment value." (PMID 36895029, 2023). "After 13 weeks, compared to the control group, pronounced increases in metastatic lung nodules and lung weight, in addition to a striking reduction in body weight, were observed in the mice injected intravenously with TTC17-knockdown cancer cells." (PMID 36895029, 2023). "Taken together, decreased TTC17 levels in BC promoted metastatic behaviors but sensitized the cancers to a panel of routine anticancer drugs, such as rapamycin and paclitaxel, as verified, providing a treatment opportunity for patients with TTC17-related molecular subtypes." (PMID 36895029, 2023).
TTC17 also shares sentences with these, for which no sentence is quoted: esophageal cancer (1 paper); pancreatic ductal adenocarcinoma (1); paraganglioma (1); pheochromocytoma (1); rectum adenocarcinoma (1); stomach adenocarcinoma (1); testicular germ cell tumor (1).